MX1 (MX dynamin like GTPase 1)
Diseases named in the same sentence as MX1 in open-access papers (continued):
Sharing a sentence is not in itself a finding about the gene and the disease.
arterial hypertension (1 paper, 2023). "The upregulation of the Mx1 and Mx2 genes has also been linked to inherited stress-induced arterial hypertension in rats." (PMID 38045685, 2023).
Arthralgia (1 paper, 2025). "MX1 expression in PBMCs was positively correlated with patient-reported ESSPRI and arthralgia Visual Analogue Scale (VAS), whereas salivary expression levels of ND6, CO1 and CO2 were negatively correlated with ESSPRI and fatigue VAS (all p<0.05)." (PMID 40360431, 2025).
Ataxia (1 paper, 2018). Ataxia refers to impaired coordination of voluntary muscle movement. "We found that blocking the type 1 interferon pathway reversed both the ataxia and decreased the expression of the type 1 interferon genes Oas1a and Mx1 in cortical tissue." (PMID 30385785, 2018). "Furthermore, PLX5562 treatment reduced ataxia at d18 and d21 post ablation and reduced type 1 interferon-mediated neuroinflammation at d10 post ablation, as measured by expression of Oas1a and mx1 at d10 post DT." (PMID 30385785, 2018).
cholangiocarcinoma (1 paper, 2024). A carcinoma that arises from the intrahepatic biliary tree (intrahepatic cholangiocarcinoma) or from the junction, or adjacent to the junction, of the right and left hepatic ducts (hilar cholangiocarcinoma). "We analyzed the expression levels of Type I interferons and ISG genes in the tumor tissues of patients and normal control tissues, revealing a consistent upregulation of ISG genes, including ISG15, MX1, MDA5, IFIT2, IFIT3, IRF1 and IRF7, in the tumor tissues of patients with cholangiocarcinoma." (PMID 38817870, 2024).
Chronic colitis (1 paper, 2023). A chronic inflammatory disease of the large intestine (colon, cecum and rectum). "Larger regions of inflammation, as measured by expression of Mx1 or pSTAT1 in the colon, was also observed indicative of chronic colitis in the gut (P<0.05 for all)." (PMID 36989320, 2023).
cognitive deficits (1 paper, 2023). "Type I interferon responses, including Mx1 and pSTAT1 expression, have been associated with neuroinflammation and cognitive deficits in untreated SIV-infection and PWH." (PMID 36989320, 2023).
dengue (1 paper, 2024). "Reduced MX1 expression may potentially result from a diminished antiviral interferon response, contributing to the severe phenotype of dengue." (PMID 38830771, 2024).
emphysema (1 paper, 2025). "In young mice, lung pathology inversely correlated with SCAT levels of Tnfa, Mx1 (epithelial lesions), and Cd4 (emphysema)." (PMID 41145556, 2025).
endotoxemia (1 paper, 2019). "In addition, endotoxemia resulted in the upregulation of multiple interferon-inducible genes such as an interferon-induced protein with tetratricopeptide Repeats (Ifit1-3), MX Dynamin Like GTPase 1 (Mx1) and Interferon regulatory element 5 (Irf5)." (PMID 32038494, 2019).
erythroleukemia (1 paper, 2022). Acute erythroid leukemia characterised by the presence of at least 50% erythroid precursors and at least 20% myeloblasts in the bone marrow. "A single spontaneous case of erythroleukemia has been reported in a Mx1-Cre–driven Brca1-deficient mouse model." (PMID 36346676, 2022).
esophageal cancer (1 paper, 2024). A primary or metastatic malignant neoplasm involving the esophagus. "Interestingly, the proteomic study on esophageal cancer also noted that the immune response genes that they identified as differentially expressed (MX1, IDO1, IFIT1, and IFIT3) did not correspond to alterations in published genomic data." (PMID 39285636, 2024).
Ewing tumors (1 paper, 2015). "Surprisingly, previously published EWS-FLI1 target genes were unchanged upon EWS-FLI1 activation in E/F; Mx1-cre mice and the expression profile of EWS-FLI1 induced leukemic cells was different from those of Ewing tumors." (PMID 26462019, 2015).
Flavivirus Infections (1 paper, 2011). Infections with viruses of the genus FLAVIVIRUS, family FLAVIVIRIDAE. "However, it is possible that MX1 may have an effect on flavivirus infections in humans." (PMID 21935451, 2011).
foot and mouth disease (1 paper, 2014). A viral infectious disease that results in infection in cattle and swine, has material basis in foot-and-mouth disease virus, which is transmitted by contaminated fomites, or transmitted by ingestion of food contaminated with infected meat or animal products. "The broad-spectrum antiviral properties of the Mx1 gene may also provide resistance to other swine infectious diseases, such as the porcine respiratory and reproductive syndrome and foot-and-mouth disease." (PMID 25408889, 2014).
gastric ulcer (1 paper, 2023). An ulcerated lesion in the mucosal surface of the stomach. "Moreover, K Marazova's study reported that MX1 (a novel salt of the active metabolite of roxatidine with a complex of bismuth and citric acid) is significantly protective against stress-induced gastric ulcers in rats." (PMID 37362100, 2023).
hantavirus infection (1 paper, 2024). "STING agonist treatment or STING overexpression significantly upregulated IFNs, pro-inflammatory cytokines (IL-1β), and interferon-stimulated genes (ISGs) (for example, Mx1 and ISG56) upon hantavirus infection." (PMID 38932148, 2024).
heart failure (1 paper, 2024). Inability of the heart to pump blood at an adequate rate to meet tissue metabolic requirements. "Another study screened key genes linked to mitochondrial function in heart failure, including the IFN-related genes RSAD2 and MX1, which exhibited substantial enrichment in myogenesis and hypoxia processes." (PMID 38753730, 2024).
hyperglycaemia (1 paper, 2024). "The axis of hyperglycaemia-higher MX1 and UBE2L6 expression-serious AS was present, which also highlighted the importance of MX1 and UBE2L6 in the comorbidity of DM and AS." (PMID 38406276, 2024). "In contrast, the expression of MX1 and UBE2L6 in the other group with stable hyperglycaemia was only 31.10 ± 19.21 and 28.21 ± 14.30, similar to that in the control group (p < 0.05 and p < 0.05, respectively)." (PMID 38406276, 2024).
injury (1 paper, 2020). Damage inflicted on the body as the direct or indirect result of an external force, with or without disruption of structural continuity. "The upregulation of MX1 and CXCL11 at mRNA and of STAT1 at the protein level in the HIVgp120tg hippocampus as well as the complete abrogation of the increases in the absence of IFNAR1 confirmed the type I IFN response we previously observed in this model system of HIV-associated brain injury." (PMID 32727588, 2020).
kidney injury (1 paper, 2023). Trauma to the kidney. "Expression of ISGs (Mx1, Isg15, Isg20, Ifitm1, Bst2, and Oas1), and immune cell markers Lyz2 and Cd68 were markedly lower in 3TC mice with FA-induced kidney injury compared to controls." (PMID 36732547, 2023).
leukopenia (1 paper, 2020). "Western blotting confirmed loss of RASA3 protein in Mx1-Cre; Rasa3 mutant red cell membranes within 2 weeks of the final Poly(I:C) injection at which time the mice are profoundly anemic and thrombocytopenic with significant leukopenia." (PMID 33370780, 2020).
liver disease (1 paper, 2017). "Also, MX1 is reported to be related with HCV clearance during acute HCV infection and after interferon therapy, and severity of liver disease." (PMID 29027943, 2017).
liver failure (1 paper, 2021). A liver disease characterized by the liver losing or has lost all of its function. "Since Mx1-Cre is expressed in both hepatocytes and Kupffer cells in the liver, we decided to examine whether liver failure upon Mof deletion is intrinsic to hepatocytes." (PMID 33376138, 2021).
lung fibrosis (1 paper, 2022). "Thus, IPF with higher levels of anti-MX1 IgA autoantibody might show more local production of TGF-β and IL-10, more apoptotic AECs in the lung, and progression of pulmonary fibrosis that is more rapid than would be found with lower levels of this autoantibody." (PMID 35391716, 2022). "Hence, hypofunctional TLR3 mutations and ELMOD2 gene deficiency in IPF may contribute to progressive lung fibrosis via a decreased type I IFN response, which suggests that induction of MX1 expression in IPF is not mediated by type I IFN." (PMID 35391716, 2022).
lymphoma (1 paper, 2022). A malignant (clonal) proliferation of B- lymphocytes or T- lymphocytes which involves the lymph nodes, bone marrow and/or extranodal sites. "Whereas NDV infected different lymphoma subtypes with variable efficiency, it induced robust expression of IFN-stimulated genes (STAT1, MX1, ISG15) across all patient samples." (PMID 36418317, 2022).
lymphopenia (1 paper, 2019). Reduction in the number of lymphocytes. "To explore the cause of the lymphopenia phenotype in Mx1-Cre+;Setd2f/f mice and to determine which step of lymphocyte differentiation was affected by Setd2 knockout, we further performed FACS analysis of HSCs and committed progenitors." (PMID 31350389, 2019).
malaria (1 paper, 2018). Malaria is a serious and sometimes fatal disease caused by a parasite that commonly infects a certain type of mosquito which feeds on humans. "The immunity related genes that are down-regulated in the malaria severity signature are: PRF1, GNLY, OAS2, MX1, OAS3 and CCL5." (PMID 29642892, 2018).
mental disorder (1 paper, 2022). A disease that has its basis in the disruption of mental process. "Eight genes are implicated in viral (SEC14L1, JMJD6, SRSF2, TMPRSS2, MX1, MX2) or bacterial (COL8A1, SPIRE1) infections, seven genes (MFSD11, METTL23, CTTNBP2, BACE2, IMPA2, MPPE1 and GNAL) are involved in mental disorders and one gene (MGAT5B) is related to the Golgi complex." (PMID 35581286, 2022).
neuroblastoma (1 paper, 2024). Neuroblastoma (NB) is the most common solid, extracranial childhood tumor. "More interestingly, antibodies induced by the MX1-NHAcGD2 conjugate bound well to IMR-32 neuroblastoma cells and had potent complement-dependent cytotoxic (CDC) effects on IMR-32 cells." (PMID 38375005, 2024). "The MX1-NHAcGD2 conjugate produces potent NHAcGD2-specific IgG antibodies that bind specifically to IMR-32 neuroblastoma cells, and antibodies mediate good CDC to kill this cell line." (PMID 38375005, 2024).
periodontal diseases (1 paper, 2025). "IFIT3 and MX1 are important mediators of inflammation and vascular diseases and may be involved in the pathogenesis of KD and periodontal diseases." (PMID 40421421, 2025).
peritoneal effusion (1 paper, 2017). "With the exception of MX1 and viperin, no distinct pattern of immune mediators was observed that distinguished between FCoV-positive cats with and without peritoneal effusion." (PMID 28388950, 2017). "However, in general, MX1, viperin, CXCL10, CCL8, RANTES, KC, MCP1, IL8, GM-CSF and IFNγ were readily detected in FCoV-positive cats whereby MX1 and viperin expression was higher in FCoV-positive cats with peritoneal effusions." (PMID 28388950, 2017).
Promyelocytic leukemia (1 paper, 2012). "Interestingly, a previous study has shown that the artificial Mx1-YFP nuclear body exhibits a very similar mobility compared with Promyelocytic leukemia and Cajal bodies." (PMID 22275876, 2012).
prostate tumor (1 paper, 2020). "Results showed that induction of HO-1 in prostate tumor cells caused a significant increase in MX1 protein levels, observed by an enhancement in the total nuclei fluorescence and in the total cell fluorescence compared with cells transfected with empty vector." (PMID 32640729, 2020).
psoriasis vulgaris (1 paper, 2022). Plaque psoriasis is the most common presentation of psoriasis. "In summary, we demonstrated that the presence of IL36G may mediate the keratinocyte expression of AVPs such as MX1, ISG15, IFI27, and IFI44L in psoriasis vulgaris." (PMID 36172384, 2022).
renal carcinoma (1 paper, 2013). A carcinoma arising from the epithelium of the renal parenchyma or the renal pelvis. "The mRNA expression levels of TIPE2 and myxoma resistance protein 1 (MX1; a type I interferon-inducible gene) were investigated in renal cancer tissues." (PMID 24137373, 2013).
rosacea (1 paper, 2023). A chronic erythematous skin disorder that affects the face. "Interestingly, whereas type I IFNs were selectively upregulated in patients with rosacea during acute flare-ups, the type I IFN response gene MX1 was upregulated in all rosacea samples as compared with healthy skin." (PMID 36633910, 2023).
schistosomiasis (1 paper, 2014). An infectious disease caused by parasitic trematodes of the genus Schistosoma that colonize human blood vessels and release eggs that can cause granulomatous reactions leading to acute (swimmer's itch or acute schistosomiasis syndrome) or chronic disease. "We infected Mx1-competent mice in the chronic phase of schistosomiasis with 60 pfu of influenza A strain hvPR8." (PMID 25398130, 2014).
scleroderma (1 paper, 2019). Scleroderma is a rare autoimmune connective tissue disorder characterized by abnormal hardening of the skin and, sometimes, other organs. "In a study of 50 scleroderma patients, an increase in MX1 expression was associated with severe disease findings, such as decreased vital capacity and digital ulcers." (PMID 31241661, 2019).
scrub typhus (1 paper, 2022). Scrub typhus is a rare dust mite-borne infectious disease caused by the Orientia tsutsugamushi bacterium and characterized clinically by an eruptive fever which is potentially serious. "Additionally, dual-RNA sequencing has uncovered a high degree of Mx1 and Oas1 gene expression in O. tsutsugamushi-infected human umbilical vein endothelial cells and a genome-wide association study of scrub typhus patients recently implicated Oas1 in susceptibility to disease." (PMID 36678402, 2022).
uterine infection (1 paper, 2022). "When comparing all four studies, a total of 24 genes were consistently upregulated by pregnancy regardless of previous uterine infection, including DKK1, MX1, MX2, STAT1 and a number of interferon stimulated genes." (PMID 35358206, 2022).
viral pneumonia (1 paper, 2018). Inflammation of the lung parenchyma that is caused by a viral infection. "MX1 is the most significant defensin-associated gene differentially expressed between bacterial and viral pneumonia (lower right, p = 1.07 × 10−9, Wilcoxin rand-sum test)." (PMID 30524393, 2018).
infection (501 papers, 2007 to 2026). The state of being infected such as from the introduction of a foreign agent such as serum, vaccine, antigenic substance or organism. "The INF-α downstream targets Isg15 and Mx1, implicated in host response to infection and inflammation, were also upregulated, particularly after 24 h of IMQ exposure." (PMID 40574053, 2025). "Blood IFI27 expression is superior to MX1 expression for diagnostic accuracy across the time course of symptomatic infection and thereby, offers higher diagnostic yield for respiratory virus infections that incur a delay between transmission and testing." (PMID 39616162, 2024). "Infection with A. actinomycetemcomitans caused a significant upregulation in the expression levels of Isg15, Mx1, Mx2, Irf3, Irf7, Tlr-2, Tnf-α, Cxcl-1, and Il-6 genes." (PMID 37929187, 2023). "Upon infection with all variants, the evaluated ISGs, Cxcl10, Isg15, and Mx-1, were upregulated and the expression levels for B.1.1 were the highest, followed by those for BA.2 and BA.5 in the lung hilum area." (PMID 37488344, 2023). "Of note, the infection caused significant upregulation in mRNA expression level of interferon-stimulated genes (Isg15, Mx1, Mx2, Irf3, and Irf7) and pro-inflammatory cytokines (Tnf-α, Cxcl-1, and Il-6 genes)." (PMID 37929187, 2023). "Further, there are 25 amino acid substitutions between KWM/Hym and M. spretus, indicating that the Mx1 protein of M. spretus has an altered function regarding the infection by the pathogenic influenza A virus." (PMID 36076303, 2022). "Low dose infections with only one pfu of either virus caused a fatal disease in Mx1-/- mice within four to five days." (PMID 33196685, 2020). "B6 mice encoding a functional murine Mx1 gene locus (Mx1) are known to be highly resistant to infections with influenza viruses of both human and avian origin such as KAN-1, A/R65 (H5N1), A/SH/1 (H7N9) and A/SC35M (H7N7)." (PMID 30945621, 2019). "Nevertheless, protective effects of IFN-λ were observed only if very low infection doses were used, presumably because mice with defective Mx1 alleles were employed for these studies." (PMID 29651984, 2018). "To better characterize how the Mx1 effects on infection response exhibit aspects of genetic dominance vs. genetic additivity, we estimated for each functional Mx1 allele a dominance index, after Kacser and Burns (1981)." (PMID 29187420, 2018). "MX1(NMX2) recapitulates many of the features associated with MX2-mediated inhibition: infection is blocked prior to nuclear cDNA import, GTPase activity is dispensable for function, and viral substrate specificity is comparable." (PMID 26446602, 2016). "Accordingly, a reduced viral load in knockout mice on day 8 post-infection was linked to elevated Isg15 and Mx1 transcript in the lungs." (PMID 26709698, 2015). "Using a recessive model, MX1 rs7280422 was significantly associated with symptomatic infection (OR = 0.25, p = 0.042)." (PMID 21935451, 2011). "We previously demonstrated that IFNAR10/0 mice with intact Mx1 alleles are highly susceptible to challenge infections with wild-type SC35M." (PMID 18787692, 2008). "In line with this hypothesis, in the current study MX1 gene expression was also delayed in human LMECs upon infection with pathogenic SEOV." (PMID 38536871, 2024). "Finally, the delay between transmission and testing in naturally acquired infection means that overall IFI27 transcripts achieve greater diagnostic accuracy than MX1 transcripts as a diagnostic triage test for respiratory virus infection." (PMID 39616162, 2024). "Thus, the functional Mx1 allele was also well induced after infection in the susceptible D2-Mx1r/r mouse strain." (PMID 38360537, 2024). "Subsequent infection of these cells causes an Mx1-mediated decrease in viral load." (PMID 36978183, 2023).